POU6F2 (POU class 6 homeobox 2)
Description:
Probable transcription factor likely to be involved in early steps in the differentiation of amacrine and ganglion cells. Recognizes and binds to the DNA sequence 5'-ATGCAAAT-3'. Isoform 1 does not bind DNA.
Synonyms: RPF-1; WT5; WTSL
Tractability: PROTAC: ubiquitination databases record sites on it.
Gene: Protein-coding gene on chromosome 7 (38,977,909 to 39,493,095, forward strand). Ensembl gene ENSG00000106536.
Subcellular location: Nucleus
Gene Ontology:
Molecular function: protein binding; DNA-binding transcription factor activity; DNA-binding transcription factor activity, RNA polymerase II-specific; RNA polymerase II cis-regulatory region sequence-specific DNA binding; DNA binding
Biological process: central nervous system development; ganglion mother cell fate determination; regulation of DNA-templated transcription; regulation of transcription by RNA polymerase II; visual perception
Cellular component: chromatin; RNA polymerase II transcription regulator complex; nucleus
Genetic constraint (gnomAD): Loss-of-function variants: 31 observed, 70.64 expected, observed/expected ratio (o/e) 0.44, 90% interval 0.33 to 0.59. The upper end of that interval is the gene's LOEUF score, 0.59, which puts it in group 2 of 6, group 1 being the genes least tolerant of losing a copy. Missense variants: 783 observed, 883.32 expected, observed/expected ratio (o/e) 0.89, 90% interval 0.83 to 0.94. Synonymous variants: 347 observed, 367.35 expected, observed/expected ratio (o/e) 0.94, 90% interval 0.86 to 1.03.
Homologues: Orthologues: macaque POU6F2 (95% identical), mouse Pou6f2 (94% identical), rabbit POU6F2 (92% identical), pig POU6F2 (91% identical), dog POU6F2 (90% identical), rat AABR07027925.1 (89% identical), chimpanzee POU6F2 (87% identical), tropical clawed frog pou6f2 (84% identical), zebrafish pou6f2 (69% identical), Drosophila melanogaster acj6 (11% identical), Caenorhabditis elegans unc-86 (10% identical). Paralogues in human: POU6F1 (36% identical), POU2F1 (18% identical), POU2F2 (15% identical), POU3F3 (15% identical), POU2F3 (15% identical), POU3F2 (15% identical), POU3F4 (14% identical), POU4F1 (13% identical), POU4F2 (13% identical), POU1F1 (13% identical), POU4F3 (12% identical), POU3F1 (12% identical), and 5 more.
Diseases named in the same sentence as POU6F2 in open-access papers:
POU6F2 is named in the same sentence as 34 diseases in open-access papers, as found by Europe PMC text mining. Sharing a sentence is not in itself a finding about the gene and the disease. The quoted sentences say what the papers report.
Wilms tumor (7 papers, 2006 to 2025). An embryonal neoplasm characterized by the presence of epithelial, mesenchymal, and blastema components. "Both POU6F1 and POU6F2 have been reported to suppress tumor proliferation, and POU6F2 mutations have been implicated in the progression of Wilms tumor, hypogonadism, and pubertal failure in human patients." (PMID 40063068, 2025). "POU6F2 has been reported to be expressed also in the developing midbrain, pituitary, and kidneys, and mutations of POU6F2 have been identified in prolactinomas and in a hereditary predisposition to Wilms tumor (nephroblastomas; 13)." (PMID 37600690, 2023). "POU6F2 belongs to the POU class homeobox family whose members are transcriptional regulators and is involved in hereditary predisposition to Wilms tumor, a pediatric malignancy of the kidney." (PMID 33245713, 2020).
glaucoma (6 papers, 2018 to 2024). Increased pressure in the eyeball due to obstruction of the outflow of aqueous humor. "POU6F2 is also a risk factor for several conditions in humans, including glaucoma, myopia, and dyslexia." (PMID 38698014, 2024). "The association of POU6F2 with the M-pathway reveals its involvement human diseases, such as glaucoma, myopia, and dyslexia." (PMID 38698014, 2024). "POU6F2 plays a very important role in corneal development and is a potential risk factor for glaucoma in humans." (PMID 31692290, 2019). "In the NEIGHBORHOOD dataset, the top 50 SNPs associated with glaucoma within the syntenic region were all found within the POU6F2 locus." (PMID 29370175, 2018). "POU6F2 is also known to be upstream of genes that play a critical role in ganglion cell death following injury and it is a potential glaucoma risk factor in humans." (PMID 29370175, 2018). "The association of POU6F2 with the M-pathway may reveal in part its role in human glaucoma, myopia, and dyslexia." (PMID 38698014, 2024). "Our data suggests that Pou6f2 modulates central corneal thickness and it may also modulate risk for glaucoma in humans." (PMID 29370175, 2018). "Pou6f2 is a genetic connection between central corneal thickness (CCT) in the mouse and a risk factor for developing primary open-angle glaucoma." (PMID 38698014, 2024). "Our findings in the macaque retina shed light on the role of POU6F2 in human glaucoma, myopia and dyslexia." (PMID 38698014, 2024). "Genes with type-specific RGC expression patterns included the glaucoma-associated genes SIX6, which was enriched in midget ganglion cells; CAV2 and POU6F2 enriched in ON parasol RGCs and AFAP1, enriched in peripheral ON parasol RGCs." (PMID 32555229, 2020). "POU6F2 appears to mark a subpopulation of RGCs that are selectively sensitive to injury in the DBA/2J mouse model of glaucoma." (PMID 29370175, 2018). "To determine if the POU6F2-positive RGCs are selectively sensitive to glaucoma, we double stained 4 young DBA/2J (2 months old) mice for POU6F2 and RBPMS and compared these values to 4 aged (8-month-old) DBA/2J mice." (PMID 29370175, 2018). "In addition, Pou6f2 may also be associated with glaucoma risk." (PMID 29370175, 2018). "These POU6F2-positive cells are sensitive to damage in the DBA/2J mouse glaucoma model." (PMID 38698014, 2024). "To determine if Pou6f2 could be a molecular link between CCT and glaucoma, we examined the distribution of POU6F2 protein and mRNA in the retina and cornea in mice." (PMID 29370175, 2018). "In addition, these POU6F2 RGCs die early in the DBA/2J model of glaucoma than most RGCs." (PMID 29370175, 2018). "Based on the distribution of POU6F2 in the cornea and retinal ganglion cells in the developing and adult mouse eye, it is tempting to suggest that Pou6f2 may be a molecular link between CCT and the potential for RGC loss in glaucoma." (PMID 29370175, 2018). "Thus, it is tempting to hypothesize that POU6F2 exerts its effects on retinal ganglion cell survival in an injury and chronic neurodegeneration (glaucoma) context by modulation of Slc30a3." (PMID 29370175, 2018). "CAV1, CAV2, and POU6F2 (POU class 6 homeobox 2) were highly co-expressed in the anterior segment and retina, suggesting that there are secondary pathways that are non-IOP related that can lead to glaucoma development." (PMID 37138096, 2023). "Thus, we are not able to definitively say that Pou6F2 is a molecular link between CCT and glaucoma." (PMID 29370175, 2018).
autism (3 papers, 2011 to 2020). Persistent deficits in social interaction and communication and interaction as well as a markedly restricted repertoire of activity and interest as well as repetitive patterns of behavior. "More specifically, genome-wide association studies have identified POU6F2 risk variants associated with psychological distress, feeling emotionally hurt, schizophrenia, autism, educational attainment and intelligence." (PMID 32048126, 2020).
schizophrenia (3 papers, 2011 to 2025). A major psychotic disorder characterized by abnormalities in the perception or expression of reality. "We found that rs7786896, located within the intronic region of POU6F2 and associated with schizophrenia, interacts with the alternative promoters (p1/p2/p4) of the POU6F2 gene." (PMID 39948187, 2025).
Anosmia (1 paper, 2023). An inability to perceive odors. "Of the eight POU6F2 variants identified in the transactivating domain, three are associated with anosmia, suggesting a role in GnRH neuronal development either directly or indirectly via changes in the olfactory system." (PMID 37600690, 2023).
autism spectrum disorder (1 paper, 2020). A spectrum of developmental disorders that includes autism, and Asperger syndrome. "In particular, the human homolog of pdm3, POU6F2, has been associated with subtypes of autism spectrum disorder (ASD)." (PMID 32202500, 2020).
Chagas disease (1 paper, 2022). A parasitic infection caused by Trypanosoma cruzi. "All those genes are involved in biological process associated to Chagas disease: nervous system (LHX6, POU6F2, MDGA1, DISC1, PCSK9), immune system (ZMIZ, HLA-DRB1), Wnt pathway (DISC1), ion transport (KCNK15, PCSK9), striated muscles (SMYD3) or ATP metabolic process (ATP5S)." (PMID 36248819, 2022).
depression (1 paper, 2021). "We detected high impact variants in genes previously implicated in depression (e.g. Gnat2), depression-like behavior (e.g. Prlr, Nlrp1a), other psychiatric disease (e.g. Pou6f2, Kdm5a, Reep3, Wdfy3), and responses to psychological stressors (e.g. Pigr)." (PMID 34285244, 2021).
Miscarriage (1 paper, 2015). A pregnancy that ends at a stage in which the fetus is incapable of surviving on its own, defined as the spontaneous loss of a fetus before the 22th week of pregnancy. "The remaining genes assayed had either very low or no expression in cultured chorionic villi from controls (PARK, LIPC, CTNNA3, EGFL6, GPM6B, RAB9A, POU6F2 and C7orf10) and were not assessed in miscarriages." (PMID 25674159, 2015).
mucoepidermoid carcinoma (1 paper, 2019). A carcinoma morphologically characterized the presence of cuboidal mucous cells, goblet-like mucous cells, squamoid cells, cystic changes, and a fibrotic stromal formation. "POU6F2 is the second most frequently mutated gene in low‐grade mucoepidermoid carcinomas." (PMID 31692290, 2019).
neuroblastoma (1 paper, 2020). Neuroblastoma (NB) is the most common solid, extracranial childhood tumor. "Functional studies are required to elucidate the roles of SMIM28, EVX2 and POU6F2 in high-risk neuroblastoma." (PMID 33245713, 2020).
viral infection (1 paper, 2020). "In contrast, α-cell-specific transcripts including GCG, ARX, BAMBI, DPP4, and POU6F2 were not affected by infection, which corresponded with our observation that viral infection was infrequent in α cells." (PMID 32093375, 2020).
tumor (9 papers, 2018 to 2025). "In conclusion, our results provide the first indication that a novel biallelic POU6F2 mutation may cause prolactinomas and that POU6F2 is a tumor suppressor in prolactinomas." (PMID 31692290, 2019). "Our study suggests that POU6F2 is also a tumor suppressor in prolactinomas and is a potential molecular therapeutic target for the control of prolactinomas." (PMID 31692290, 2019). "POU6F2 was also highly expressed in normal tissue compared with tumor tissue and patients with high expressions of POU6F2 had a significantly worse overall survival (OS) rate (p = 0.0032) compared to patients with low expressions of POU6F2, but this was not statistically significant in DFS." (PMID 37296706, 2023). "This pattern suggests that POU6F2 is a tumor suppressor in prolactinomas." (PMID 31692290, 2019).
brain disease (1 paper, 2022). "We then performed selective pressure analysis on the polyQ tract of the other seven brain disease-related proteins, and of two proteins not-associated with any disease (POU6F2 and ZNF384)." (PMID 34974533, 2022).
cancer (1 paper, 2025). A tumor composed of atypical neoplastic, often pleomorphic cells that invade other tissues. "We also identified novel TFs such as NOBOX in HNSC, ZNF280C in KIRP, and POU6F2 in LUSC, which potentially regulate cancer-specific regulatory networks yet remain relatively understudied in those cancer types." (PMID 40748712, 2025).
psychiatric disease (1 paper, 2021). "Further, Pou6f2, Kdm5a, Reep3, Wdfy3 have been implicated in psychiatric diseases such as autism and Pigr was found to be involved in response to psychological stress." (PMID 34285244, 2021).
POU6F2 also shares sentences with these, for which no sentence is quoted: Alzheimer disease (2 papers); hypogonadism (2); bipolar disorder (1); cardiomyopathies (1); cardiovascular diseases (1); cavernous cerebral malformation (1); diabetes (1); dyslexia (1); glioma (1); infection (1); Intellectual disability (1); ischemic stroke (1); Leiomyomatosis and Renal Cell Cancer (1); myopia (1); Parkinson disease (1); primary open-angle glaucoma (1); psychological distress (1); unipolar depression (1).